Y_RNA (Y RNA )
Gene: Miscellaneous RNA gene on chromosome 17 (81,573,490 to 81,573,602, forward strand). Ensembl gene ENSG00000207021.
Homologues: Orthologues: chimpanzee Y_RNA (99% identical), macaque Y_RNA (91% identical), guinea pig Y_RNA (86% identical). Paralogues in human: RNY1 (88% identical), Y_RNA (88% identical), Y_RNA (87% identical), Y_RNA (86% identical), RNY1P11 (85% identical), Y_RNA (85% identical), Y_RNA (84% identical), RNY1P8 (83% identical), Y_RNA (83% identical), Y_RNA (82% identical), RNY1P10 (81% identical), RNY1P7 (81% identical), and 99 more.